PRTFDC1 (phosphoribosyl transferase domain containing 1)
Description:
Has low, barely detectable phosphoribosyltransferase activity (in vitro). Binds GMP, IMP and alpha-D-5-phosphoribosyl 1-pyrophosphate (PRPP). Is not expected to contribute to purine metabolism or GMP salvage.
Synonyms: HHGP
Tractability: Small molecule: a structure with a bound ligand is known. PROTAC: ubiquitination databases record sites on it.
Gene: Protein-coding gene on chromosome 10 (24,848,614 to 24,952,606, reverse strand). Ensembl gene ENSG00000099256.
Subcellular location (Human Protein Atlas): Nucleoplasm; Cytosol; Golgi apparatus
Gene Ontology:
Molecular function: hypoxanthine phosphoribosyltransferase activity; protein binding; protein homodimerization activity; magnesium ion binding
Biological process: GMP catabolic process; guanine salvage; purine ribonucleoside salvage
Cellular component: cytosol
Genetic constraint (gnomAD): Loss-of-function variants: 38 observed, 34.71 expected, observed/expected ratio (o/e) 1.09, 90% interval 0.84 to 1.43. The upper end of that interval is the gene's LOEUF score, 1.43, which puts it in group 5 of 6, group 1 being the genes least tolerant of losing a copy. Missense variants: 256 observed, 277.06 expected, observed/expected ratio (o/e) 0.92, 90% interval 0.83 to 1.02. Synonymous variants: 85 observed, 94.53 expected, observed/expected ratio (o/e) 0.9, 90% interval 0.75 to 1.08.
Homologues: Orthologues: macaque PRTFDC1 (99% identical), dog PRTFDC1 (94% identical), chimpanzee PRTFDC1 (93% identical), rat Prtfdc1 (91% identical), rabbit PRTFDC1 (86% identical), pig PRTFDC1 (85% identical), tropical clawed frog prtfdc1 (70% identical), zebrafish prtfdc1b (64% identical), zebrafish prtfdc1a (62% identical), zebrafish hprt1l (57% identical), Drosophila melanogaster Pgm1 (20% identical), Caenorhabditis elegans pgm-1 (20% identical). Paralogues in human: HPRT1 (65% identical), PGM2 (24% identical), PGM5 (24% identical), PGM2L1 (23% identical), PGM1 (19% identical), PGM3 (12% identical).
Diseases named in the same sentence as PRTFDC1 in open-access papers:
PRTFDC1 is named in the same sentence as 10 diseases in open-access papers, as found by Europe PMC text mining. Sharing a sentence is not in itself a finding about the gene and the disease. The quoted sentences say what the papers report.
stress-related disorder (2 papers, 2024 to 2025). Stress-related disorders are mental health disorders that are a result of an atypical response to both short and long-term anxiety due to physical, mental, or emotional stress. "Previous research has demonstrated that PRTFDC1 is closely associated with various neuropsychiatric and stress-related disorders, such as dissociative amnesia and acute stress reaction, and plays important roles in the occurrence and progression of multiple cancers." (PMID 41472177, 2025).
B cell lymphoma (1 paper, 2025). "To investigate the expression of PRTFDC1 in TGCT tissues, we analyzed 48 human testicular tissue microarrays, excluding five cases of B cell lymphoma." (PMID 40241724, 2025).
breast carcinoma (1 paper, 2025). "However, high expression of PRTFDC1 is positively correlated with the triple-negative basal-like immune-suppressed breast cancer subtype (TNBC-BLIS), which is considered one of the poorest prognostic subtypes of breast cancer." (PMID 40241724, 2025).
oral squamous cell carcinoma (1 paper, 2025). "Studies suggest that in oral squamous cell carcinoma and ovarian cancer, PRTFDC1 may have tumor-suppressive effects." (PMID 40241724, 2025).
testicular germ cell tumor (1 paper, 2025). A germ cell tumor arising from the testis. "Patients with testicular germ cell tumors exhibiting low PRTFDC1 expression show greater sensitivity to immunotherapy, highlighting its potential as a prognostic biomarker and therapeutic target." (PMID 40241724, 2025). "Chen and colleagues report that high expression of PRTFDC1 is frequently observed in testicular germ cell tumors and correlates with poorer prognosis." (PMID 40241724, 2025).
tumor (4 papers, 2011 to 2026). "In TGCT, our study found that high expression of PRTFDC1 is associated with poor prognosis, which contradicts its tumor-suppressive role in other cancers." (PMID 40241724, 2025). "In contrast, in the low PRTFDC1 expression group, tumor cells may depend more on these mutated oncogenes and their associated signaling pathways to drive proliferation and survival." (PMID 40241724, 2025). "Conversely, in cancers where PRTFDC1 acts as a tumor suppressor, strategies to enhance its expression or function should be considered to harness its potential in inhibiting tumor growth." (PMID 40241724, 2025). "Prtfdc1 belongs to the purine/pyrimidine phosphoribosyltransferase family and has been identified as a genetic modifier of hypoxanthine phosphoribosyltransferase as well as a potential tumor suppressor." (PMID 41596666, 2026). "In TGCT or TNBC-BLIS, where PRTFDC1 may promote tumor progression, its expression could be reduced or its associated signaling pathways blocked to inhibit its function." (PMID 40241724, 2025). "We hypothesize that high PRTFDC1 expression may enhance purine nucleotide reutilization, thereby supporting the tumor cells' dependence on proliferative signals." (PMID 40241724, 2025). "Genes that were decreased by only CBP30+CPTH2 treatment were nuclear membrane proteins, including Emd, which regulates gene expression through the regulation of nuclear and cytoskeletal actin polymerization, and Prtfdc1, which inhibits cell proliferation in tumor cells." (PMID 36417410, 2022). "Consequently, we speculate that in the high PRTFDC1 expression group, tumor cells may be more reliant on the purine nucleotide salvage pathway to promote proliferation, rather than on the signaling pathways activated by KIT, NRAS, or KRAS mutations." (PMID 40241724, 2025). "In addition, while PRTFDC1 has been identified as a potential tumor suppressor, how it functions in this capacity is also unknown." (PMID 21818316, 2011). "Additionally, we observed a negative correlation between PRTFDC1 expression and CD8+ T cell infiltration.CD8+ T cells recognize tumor-associated antigens, selectively kill tumor cells, and induce anti-tumor responses, with increased infiltration typically associated with better prognosis." (PMID 40241724, 2025).
cancer (3 papers, 2022 to 2025). A tumor composed of atypical neoplastic, often pleomorphic cells that invade other tissues. "According to the GSEA results, high expression of PRTFDC1 activates pathways associated with cancer progression, such as the TGF-β signaling pathway, while inhibiting immune-related pathways." (PMID 40241724, 2025). "Expression of Emd, a nuclear membrane protein, and Prtfdc1, which is involved in cancer cell proliferation, were altered significantly in CBP30+CPTH2 samples." (PMID 36417410, 2022). "This discrepancy may arise from the different biological functions and interaction networks of PRTFDC1 in distinct cancers." (PMID 40241724, 2025). "Therefore, personalized treatment strategies should be based on the specific role of PRTFDC1 in each cancer type." (PMID 40241724, 2025). "In addition, the role of genes closely related to HPRT1, such as GMPR2 and phosphoribosyl transferase domain containing (PRTFDC1), in pan-cancer needs to be addressed." (PMID 38159260, 2024). "PRTFDC1 may exhibit different roles across various cancer types." (PMID 40241724, 2025).
PRTFDC1 also shares sentences with these, for which no sentence is quoted: dissociative amnesia (1 paper); HPRT-deficiency (1); ovarian carcinoma (1).